SOX2 (SRY-box transcription factor 2)
Diseases named in the same sentence as SOX2 in open-access papers (continued):
Sharing a sentence is not in itself a finding about the gene and the disease.
tumor (continued). "Though SOX2 over-expression was reported to associate with lower tumor grade, smaller tumor size and lower probability of invasion and metastasis and former and current smoking status, here our results showed that SOX2 positive expression was not correlated with these clinicopathological parameters." (PMID 23990933, 2013). "SOX2 overexpression is associated with aggressive disease in several tumor types." (PMID 23620753, 2013). "In addition, elevated tumor SOX2 resulted in 36% reduction in risk for all NSCLC patients at Cox univariate analysis (hazards ratio-HR = 0.64 confidence interval-CI (0.46,0.91), p = 0.01)." (PMID 23620753, 2013). "Moreover, SOX2 expression is associated with aggressive phenotype and poor prognosis in several tumor types." (PMID 23620753, 2013). "In this study, we characterized the epigenetic regulation of the pluripotency-associated genes NANOG, OCT4, c-MYC, KLF4, and SOX2 in a variety of cancer cell lines and in primary tumor samples, and investigated the re-activation of pluripotency regulatory circuits in cancer progression." (PMID 24023739, 2013). "Supporting this hypothesis, it was suggested that knocking down Sox2 and Oct4 in tumor-initiating cells would lead to the loss of the self-renewal, proliferating and tumorigenic capacities and result in CSC-like cell apoptosis of cancer cells." (PMID 22837720, 2012). "The reduction in miR-21 expression could be coupled to a decrease in SOX2 expression, loss of tumor-initiating ability of the cells and induction of oligodendrocyte differentiation." (PMID 22931209, 2012). "However, high SOX2 expression (score 3) was associated with larger tumor size (p = 0.047) and positive lymph node status (0.018)." (PMID 21276239, 2011). "Finally, we wanted to clarify, if the poorer outcome of CCs with high SOX2 expression is associated with an increased occurrence of distant metastases, which is known to be the best predictor for an unfavourable course of tumour diseases." (PMID 22168803, 2011). "SLC16A4 expression was found to be significantly negatively correlated with tumor stemness as quantified by RNA-based stemness scores (RNAss) (r = −0.585) and similarly showed a strong negative correlation with the expression of the stemness-associated marker gene SOX2 (r = −0.551)." (PMID 40867526, 2025). "Moreover, SOX2 has been described as a prognostic factor for different types of cancers, although there are reports on an association with both, good and bad outcome, depending on the context of tumor entity and stage of disease." (PMID 39180200, 2025). "However, the underlying mechanism by which SOX2 was upregulated in tumor tissues remained unclear." (PMID 35473511, 2022). "Interestingly, it has been shown that the MYC-driven transformation of SOX2+ astrocyte progenitor cells give rise to group 3 MB, suggesting that SOX2+-tumor-associated astrocytes might have different tumorigenic functions in the MB subgroups." (PMID 36291792, 2022). "Therefore, we used a stemness gene associated with tumor cell heterogeneity and SOX2, SOX4, SOX9, basal cell markers KRT5, KRT14, immune genes PD-Ll and epithelial-mesenchymal transition E-cadherin to study heterogeneous cell and malignant transformation mechanisms." (PMID 36056339, 2022). "However, the employment of specific inhibitors of Glut1 transporters, such as WZB117, has been demonstrated to affect tumor insurgence through the downregulation of stemness-associated genes, such as SOX2, NANOG and BMI1 in different cancers including pancreatic, ovarian and glioblastoma cancer." (PMID 34249759, 2021). "By multivariate survival analysis, Sox2 was associated with poor cancer-specific survival (Hazard Ratio = 1.48, 95% confidence interval 1.04–2.11, p = 0.0292), independently of the pathologic tumor size, pathologic nodal stage, distant metastasis, and AR expression." (PMID 33553286, 2020). "Additionally, SOX2 is associated with tumor progression and prognosis in urothelial carcinoma." (PMID 32523078, 2020).
tumor (continued). "However, tumor susceptibility of SOX2+ cells seems oncogene-specific." (PMID 31041783, 2019). "In addition to being essential for maintaining cell stemness, SOX2 has been identified as an oncogenic factor in processes associated with tumor progression including cell proliferation and tumorigenesis of ESFT; however, details of the mechanism are poorly understood." (PMID 26969300, 2016). "In addition, Sox2 could also be suppressed by AR and closely associated with castration-resistant tumor growth." (PMID 24618337, 2014). "The fact that in our study SOX2 seropositive patients' tumors on occasion contained very few cells could be reflecting the fact that such tumors undergo immune-editing, and reach a state of equilibrium between the tumor and the immune response following a loss of most SOX2 expressing cells." (PMID 24940116, 2014). "Moreover, over-expression of Oct4, Sox2 and Nanog has been found in poorly differentiated tumors, which could be associated with tumor progression and metastasis." (PMID 23024790, 2012). "Hence, our present data suggest that SOX2 plays a crucial role in gastric carcinogenesis as a tumour suppressor, and loss of SOX2 expression may cause gastric epithelial cells develop into carcinomas." (PMID 18268498, 2008). "Although human NC cell studies have shown that SOX2 knockdown reduces colony and tumorsphere formation but has limited effects on proliferation, our results indicate that SOX2 is dispensable for tumor initiation and maintenance in mice." (PMID 41266112, 2026). "On the basis of the Wilcoxon rank sum exact test, EB-cSCC showed a significantly higher percentage of SOX2-positive tumor cells than UV-induced cSCC (W = 75, P = .01327)." (PMID 41189680, 2026). "Considering the potential role of SOX2 in tumor initiation of the aggressive EB-cSCC, targeting SOX2 presents a promising approach for anticancer therapy." (PMID 41189680, 2026). "In silico analyses reveal the co-expression of SOX2 and chromaffin cell markers in the tumour and reveal the active proliferation of these double-positive cells." (PMID 42023823, 2026). "Overall, these data suggest that SOX2 is a cell-specific requirement for the IVL+ tumour-resistant progenitor population to initiate cSCC." (PMID 41507151, 2026). "Because Krt14-Cre remains active in NC cells, any residual floxed alleles would be deleted during tumor progression, making it highly improbable that a Brd4::Nutm1-positive tumor retains intact Sox2." (PMID 41266112, 2026). "In this study, we intended to determine if SOX2+ cells in PCCs and PGLs can behave as tumour-initiating stem cells." (PMID 42023823, 2026). "One of our key findings was that SOX2 activation in the IVL+ tumour-resistant population is sufficient to render this population susceptible to oncogenic transformation." (PMID 41507151, 2026). "These interactions can reprogram stem cell fate toward tumor-suppressive or tumor-promoting outcomes, reactivate multipotency genes such as Nanog, Sox2, and Oct4, and thereby shape self-renewal, differentiation, and malignant transformation." (PMID 41596284, 2026). "Unlike other NC markers, such as BRD4::NUTM1 and p63, which are diffusely expressed across most tumor cells, SOX2 is restricted to discrete subpopulations, often located near the tumor margin adjacent to the morphologically normal tissue." (PMID 41266112, 2026). "siRNA-based RNAi, for example, excels in sequence-specific SOX silencing, with preclinical NSCLC models showing decreased tumor growth and stemness following SOX2 or SOX9 knockdown." (PMID 41268614, 2026).
tumor (continued). "Because SOX2 seems to be an important regulator of cancer stem cell function and of tumor-initiating potential in sporadic cSCCs, we surmised that SOX2 expression in EB-cSCCs can contribute to its aggressive phenotype." (PMID 41189680, 2026). "In human NC cell lines, RNAi-based SOX2 knockdown induces cellular differentiation and impairs tumor sphere and colony formation, albeit with only moderate effects on proliferation." (PMID 41266112, 2026). "Similar results were obtained in HRAS-driven tumours, where SOX2 expression was only seen in those arising from the IVL+ population." (PMID 41507151, 2026). "For instance, tumor-intrinsic SOX2 signaling in NSCLC promotes the recruitment of regulatory T cells (Tregs) by upregulating CCL2, thereby mediating resistance to ICIs." (PMID 41268614, 2026). "SOX2-positive cells are known for their stem-like properties and play a significant role in tumor resistance and recurrence in GBM." (PMID 41596406, 2026). "We confirmed SOX2 upregulation in Ivl:BRAFV600E tumours compared to K5:BRAFV600E or K14:BRAFV600E tumours by IHC." (PMID 41507151, 2026). "Comparable with the percentage of SOX2-positive tumor cells, EB-cSCC exhibited a significantly higher H-score than UV-induced cSCC (W = 76, P = .01013)." (PMID 41189680, 2026). "Six of 9 EB-cSCC (67.6%) showed a positive SOX2 expression in especially tumor cells along the tumor–stroma interface (TSI), whereas the UV-induced cSCC demonstrated absent nuclear SOX2 expression (0 of 10)." (PMID 41189680, 2026). "This SOX2-driven stemness state also appears to be activated in tumours derived from the LGR6+ population in the DMBA/TPA model." (PMID 41507151, 2026). "To this end, we interbred an allele that allows the inducible overexpression of SOX2 from the Rosa26 locus [Rosa26LSL-SOX2-IRES-eGFP (hereafter SOX2LSL)] into the IVL+ tumour-resistant population." (PMID 41507151, 2026). "Although the median percentage of SOX2-positive tumor cells in UV-induced cSCC is low (3.83%), all UV-induced cSCCs were defined as having absent nuclear SOX2 staining in the semiqualitative assessment." (PMID 41189680, 2026). "In vivo, disruption of the NUP93/SOX2/G3BP1 axis suppressed tumor growth and synergized with gemcitabine." (PMID 41896201, 2026). "We observed a significant increase over time in the interactions between SOX2/OLIG2 high tumor cells and different tumor cell populations, including p-TYR high and translating GFAP- tumor cells." (PMID 41568176, 2026). "This distinction is particularly important given prior reports linking SOX2 to pluripotency, squamous lineage fidelity, and tumor-initiating potential." (PMID 41266112, 2026). "In a murine cSCC model of the same study, SOX2 promoted the expansion of so-called tumor-initiating cells along the TSI, which have the ability to self-renew, give rise to differentiated cells, and form new tumors." (PMID 41189680, 2026). "SOX2 activation in this population, combined with an oncogene, results in a clonal behaviour similar to the K14/K5+ tumour-primed population and promotes the re-acquisition of stemness and tumour-initiating capabilities in the skin's basal compartment." (PMID 41507151, 2026). "Depletion of SOX2-expressing cells in invasive BC models led to enhanced tumor regression, underscoring the essential role of SOX2-positive cells in BC progression." (PMID 40177538, 2025). "Consistently, SOX2 maintains progenitor identity through regulating their expression in CP tumors and during development, whereas LMX1A and LMX1B support SOX2 functions in tumor cell proliferation." (PMID 40128799, 2025). "Atonal Homolog 1 (ATOH1) and SOX2 are PTFs that play vital roles in Merkel cell differentiation, and tumor-suppressing pathways." (PMID 40589575, 2025).
tumor (continued). "In a heterotopic xenograft mouse model, DAP was intraperitoneally administered to immunocompromised mice, which significantly reduced tumor volume and weight and SOX2-positive cells in tumors, indicating the reduction of OSC stemness and tumorigenicity." (PMID 40730548, 2025). "Simultaneously, OGT-mediated modification of SOX2 at Ser246 stabilises its nuclear localisation, further supporting tumour development." (PMID 41463025, 2025). "Elevated SOX2 expression in HPV-positive cancers contributes to tumor initiation, therapy resistance, and metastasis by promoting cancer stem-like phenotypes." (PMID 40589575, 2025). "Sox2 reactivates embryonic transcriptional programs that enable dedifferentiation, lineage switching, and adaptive tumor evolution." (PMID 41023204, 2025). "Western blotting (WB) and immunohistochemical staining (IHC) results showed higher SOX2 expression in tumor tissues versus paracancerous tissues from OS patients in Orthopedic Oncology Department of Shanghai Changzheng Hospital." (PMID 39994220, 2025). "Initiating treatment when tumors averaged approximately 100 mm3, pCRISPRi targeting ΔNp63 or SOX2 significantly slowed tumor progression and induced apoptosis." (PMID 40871074, 2025). "The collaborative actions of NANOG, OCT4, and SOX2 contribute to the survival and persistence of CSCs, making them key factors in tumor recurrence and therapeutic resistance." (PMID 40759634, 2025). "Taken together, the coordination of TGIF2/SOX2 promotes subcutaneous tumor size and liver metastasis by activating EMT and EGFR/MAPK signaling." (PMID 39781447, 2025). "These factors significantly upregulate transcription factors such as Sox2, Oct4, Klf4, and Nanog, which are known to reprogram differentiated tumor cells into stem-like phenotypes." (PMID 40253386, 2025). "In a comparative oncology investigation, SOX2 overexpression was also found in tissue samples from many types of canine neoplasia." (PMID 40563676, 2025). "Pluripotency-associated factors such as OCT4 (POU5F1), SOX2, and NANOG are frequently implicated in dedifferentiation and cancer stem cell (CSC) maintenance, allowing tumor cells to regain developmental plasticity." (PMID 40722714, 2025). "SOX2, located on 3q26.3–q27, is identified as a major oncogene in OSCC, associated with tumor proliferation, metastasis, therapeutic resistance, and the facilitation of epithelial–mesenchymal transition (EMT)." (PMID 40227667, 2025). "Specifically, SOX2 is crucial for tumor initiation and CSC function in squamous cell carcinomas, including esophageal squamous cell carcinoma." (PMID 40227962, 2025). "Immunostaining slides from NPC patients confirmed the existence of the SOX2 and TrkB proteins in this tumor type." (PMID 40133476, 2025). "Poly (A:U) treatment of tumor spheres induces the expression of SOX2, which was reduced by the treatment with ASA, MF, and KW." (PMID 40647457, 2025). "To improve the reliability of our tumor cell comparisons, we implemented a two-step filtering strategy to identify and exclude SOX2+ AOIs with low tumor purity." (PMID 40960500, 2025). "In breast and colorectal cancers, KLF4 has been shown to interact with other key transcription factors like Sox2 and Oct4 to regulate the balance between self-renewal and differentiation, thereby influencing tumor progression and response to therapy." (PMID 40868290, 2025). "In agreement, co-immunoprecipitation studies demonstrated the association of SOX2 and OTX2 in CP tumor cells." (PMID 40128799, 2025). "Consistently, SOX2 expression was observed across histological grades in human CP tumor samples that exhibited variations in positive staining area and signal intensity." (PMID 40128799, 2025).
tumor (continued). "This is consistent with literature linking high SOX2 levels to advanced tumor grades and enhanced self‐renewal and tumorigenicity in GSCs." (PMID 39968701, 2025). "This process not only increases the delivery of oxygen and nutrients to the growing tumor cells but also promotes the expression of c‐Myc and Sox2, which are essential for sustaining tumor growth and progression." (PMID 41049266, 2025). "Our lab recently described how stem cell-driving events coordinated by Oct4 and Sox2 enhance tumorigenicity and tumor cell-mediated immunosuppression." (PMID 40277917, 2025). "Deletion of Sox2 has additionally been shown to prevent tumor initiation and impair CSC proliferation." (PMID 40868290, 2025). "An alternative strategy is targeting WDR5, crucial for GSC self-renewal and tumor initiation, by disrupting the epigenetic maintenance of GSCs and circumventing the challenges of directly targeting transcription factors like SOX2." (PMID 40565099, 2025). "On one hand, DDR1-STAT3 phosphorylation upregulates SOX2, enhancing cancer stemness and supporting the invasion and survival of circulating tumor cells." (PMID 40563472, 2025). "PHGDH ablation decreased SOX2 and Olig2 positive tumor cells in GBM xenografts, indicating a reduced GSC reservoir." (PMID 40102981, 2025). "All detected metastatic lesions in AKPS mice were SOX2 positive, strongly linking SOX2 expression to enhanced metastasis in the AKPS tumor model." (PMID 40179020, 2025). "Tumor cell groups were assigned based on chromatin accessibility of genes expressed in tumor cells, including Hes5 and Sox2, whereas regulatory regions of Lmx1a and Lmx1b were accessible only in tumor cell groups." (PMID 40128799, 2025). "Immunofluorescence demonstrated that Ki-67 expression was reduced after Sox2 knockdown in tumor cells infected with control viruses, indicative of decreased tumor cell proliferation." (PMID 40128799, 2025). "Specifically, we identified that LPCAT1 serves as a key mediator connecting SOX2 transcriptional regulation with cholesterol biosynthesis, thereby creating a vicious cycle that promotes tumor aggressiveness." (PMID 41358198, 2025). "This overexpression often promotes tumor progression, enhances metastasis, reduces radiosensitivity, and worsens overall survival, partly by activating pathways such as Wnt, Sox-2, and TGF-β1." (PMID 40429363, 2025). "SOX2 features prominently in gene panels for GBM classification due to its central role in tumour aggressiveness." (PMID 41179304, 2025). "Statistical analysis showed that high expression rate for SOX2 is higher in tumor tissues versus paracancer tissues." (PMID 39994220, 2025). "These glioma stem cells (GSCs) arise through the reprogramming of more differentiated tumor cells induced by specific transcription factors, known as the Yamanaka factors (e.g., Oct4, Sox2, c-Myc, Klf4)." (PMID 40277917, 2025). "Compared to the untreated group, there were reduced expressions of the pAkt, Akt, and Sox2 proteins in PCA-treated 4T1 tumor tissues." (PMID 40076435, 2025). "When Braf CA/+PtenΔ/+Sox2fl/fl, Braf CA/+PtenΔ/+Sox2fl/+, Braf CA/+PtenΔ/+Sox2+/+ mice were treated with tamoxifen at p2-4, a marked Sox2 gene dosage-dependent decrease in tumor incidence was observed." (PMID 40571713, 2025). "This dual inhibition not only reduces the sustained activation of the signaling pathway but also effectively suppresses the proliferation and survival of SOX2 + tumor stem cells." (PMID 40696244, 2025). "Secondly, the study lacks to provide mechanistic insights into how SOX2 influences tumor biology or treatment response, despite the fact that it demonstrates an association between SOX2 expression and improved survival." (PMID 40227667, 2025). "After filtering, the expression of SOX2 and AIF1 (which encodes the protein IBA1) aligned with the expected segmentation, confirming distinct transcriptional profiles between tumor cells and TAMs." (PMID 40960500, 2025).